TIGIT (T cell immunoreceptor with Ig and ITIM domains)
Diseases named in the same sentence as TIGIT in open-access papers (continued):
Sharing a sentence is not in itself a finding about the gene and the disease.
cancer (continued). "Using virtual screening in combination with comprehensive methods, we redefined the function of the small molecule compound liothyronine in blocking the interaction between TIGIT and PVR for cancer immunotherapy." (PMID 34068552, 2021). "Along with its co-inhibitory receptor CD96 (TACTILE), TIGIT can bind to ligand CD155, also known as the poliovirus receptor (PVR), which is upregulated in many cancers." (PMID 33946954, 2021). "This review discusses the recent discoveries regarding the roles of TIGIT and CD226 in immune cell function and their potential application in cancer immunotherapy." (PMID 33670993, 2021). "Therefore, the development of TIGIT/PVR inhibitors may have potentials in cancer immunotherapy." (PMID 33557880, 2021). "TIGIT, PD-1 and TIM-3 are co-inhibitory receptors highly expressed by exhausted T cells in chronic infections and cancer." (PMID 34820398, 2021). "However, a specific function of TIGIT in pan-cancers remains largely unknown." (PMID 34795387, 2021). "T cell Ig and ITIM domain (TIGIT)/CD226 pathway has a critical role in regulating T cell responses and has come to the forefront in cancer as a promising immunotherapeutic target." (PMID 33413573, 2021). "In cancer, TIGIT is overexpressed and CD226 is underexpressed, and the TIGIT/CD226 pathway has gained attention as a potential clinical target for improving antitumor immune responses." (PMID 33413573, 2021). "TIGIT expression also positively correlated with CTLA4, PDCD1 (PD-1), CD274 (PD-L1), ICOS in most of the cancer types." (PMID 34795387, 2021). "Our research provides a promising candidate for cancer immunotherapy, bridging the innate and adaptive immunity by a CD47/SIRPα and TIGIT/PVR blockade." (PMID 34068552, 2021). "Overexpression of PVR on cancer cells can restrain T cell and NK cell responses because PVR can negatively manipulate TIGIT functions." (PMID 33557880, 2021). "Tregs are superior in suppressing T cell activation, and anti-TIGIT treatment reduces the proportion of CD4+ Tregs and inhibits the suppressive ability of Tregs, suggesting another pathway for cancer immunotherapy." (PMID 34433460, 2021). "Several humanized anti-TIGIT mAb (AB154 and Etigilimab) have already entered clinical trials in cancer therapy, alone and in combination with anti-PD-1." (PMID 32432050, 2020). "Other IRs have also been discussed as potential targets for cancer immunotherapy, including Tim3, BTLA, and TIGIT." (PMID 32451453, 2020). "Immune checkpoint receptors, such as TIGIT, PD-1 and CTLA-4, have been discovered to be highly expressed in numerous types of cancer, and they are currently being targeted to improve antitumor and T or NK cell responses." (PMID 32903786, 2020). "On the other hand, TIM-3 blockade in some cancers has been shown to downregulate CTLA-4 and TIGIT expression levels and significantly decrease the development of cancer." (PMID 33425759, 2020). "TOX knockdown in the human TI CD8+ T cells resulted in downregulation of PD-1, TIM-3, TIGIT, and CTLA-4, which suggests that TOX promotes intra-tumoral T cell exhaustion by upregulating IC proteins in cancer." (PMID 32111241, 2020). "The results showed that CTLA-4, IDO1, LAG-3, TIGIT and PD1 were specifically increased most in TBNC among different types of cancer." (PMID 32602545, 2020). "CD155, CD96, or TIGIT blockade is able to reverse the dysfunction of T cells and NK cells in the TME in many types of cancers." (PMID 32714324, 2020). "In fact, the role of TIGIT and CD96 in NK cell exhaustion in various cancers is under investigation, and further revelations are needed to establish their potential for targeting either as monotherapy or in combination with other checkpoints." (PMID 32117298, 2020). "It is also upregulated in human malignancies and a number of anti-TIGIT antibodies (e.g., etigilimab/OMP-313M32, MTIG7192A, and AB154) are now being evaluated in early phase clinical trials as anti-cancer agents." (PMID 32195317, 2020).
cancer (continued). "Our co-expression analysis appears to underscore the prominent role of the PD-1, TIGIT, and Tim-3 IRs on CD8 TILs in T-cell exhaustion for multiple types of cancer." (PMID 31709176, 2019). "Further, blocking CD96 reduced the number of B16F10 metastases in Tigit−/− mice compared to wildtype mice, indicating the synergistic potential of blocking CD96 and TIGIT in treating cancer." (PMID 31681269, 2019). "In this paper, we found that aspirin attenuates cancer cell proliferation and induces CRC cells apoptosis by down‐regulating the expression of TIGIT, which provides new evidence for the application of aspirin in cancer treatment." (PMID 31090213, 2019). "Previous studies show that the upregulation of PD‐1 and TIGIT on antigen‐specific CD8+ T cells contribute to their exhaustion in chronic viral infection and cancer." (PMID 29349889, 2018). "These multi-functional NK cells are capable of competitively binding to CD155+ cancer cells, displacing the inhibition induced by CD155/TIGIT interaction, and blocking CD73." (PMID 30400822, 2018). "Regarding receptors, there exhibited a strong correlation with PD-1 and receptors including TIGIT, CTLA-4, LAG3, BTLA, ICOS, TNFRSF9, CD27 in most types of cancer." (PMID 30607140, 2018). "Together, these observations suggest that TIGIT and CD226 potentially regulate antitumor T-cell responses and warrant further investigation of these molecules in human cancers." (PMID 30400822, 2018). "TIGIT and CD226 are paired receptors that compete for shared ligands CD155 (PVR) and CD112 (Nectin-2) expressed by cancer and antigen-presenting cells." (PMID 30400822, 2018). "These immune-related genes include those that are established or promising targets for cancer immunotherapy such as CTLA4, PD1, PD-L1, PD-L2, IDO1, LAG3, and TIGIT." (PMID 30089500, 2018). "In NK cells, TIGIT competes with the DNAM-1 (CD226) activating receptor for their common ligands CD112 (PVRL2) and CD155 (PVR) expressed on many cancer cells." (PMID 29023417, 2017). "Similar results were also obtained when analyzing PD-1, TIM-3 and TIGIT expressions by MFI on TILs, AEM and PBMCs from cancer patients." (PMID 27577071, 2016). "This review provides a comprehensive overview of the regulation and therapeutic targeting of immune checkpoint proteins in cancer, covering both classical checkpoints, including PD-1, PD-L1, and CTLA-4, and emerging targets such as LAG-3, TIM-3, TIGIT, BTLA, SIRP-α, CD200, ILT4, and CD24." (PMID 42279386, 2026). "TIGIT and CD155 have been suggested as promising new targets for cancer immunotherapy." (PMID 40822998, 2025). "Furthermore, the regulatory network of MHC-II+ cancer cells revealed interactions between PVR and coinhibitory receptors including TIGIT and CD96, which induce CD8+ T-cell exhaustion and Treg activation, and subsequently facilitate immune evasion." (PMID 41281745, 2025). "Notably, combining TLR agonists with immune checkpoint inhibitors such as PD-1/PD-L1, CTLA-4, TIGIT, and LAG3 has yielded synergistic effects and improved therapeutic outcomes across various cancer models." (PMID 41228373, 2025). "Furthermore, TIGIT potentially inhibits DNA damage (16%), hormone androgen receptor (AR) (16%), and receptor tyrosine kinase (RTK) (12%) pathways in pan-cancer." (PMID 40076932, 2025). "TIGIT-expressing ILC2s have been recently described in a model of chronic allergy disease, but data related to their expression in cancer have not be reported." (PMID 39858045, 2025). "The engagement of TIGIT with its binding partners, poliovirus receptor (PVR) (CD155), nectin-2 (CD112), and nectin-4 (PVRL4)—plays a pivotal role in modulating immune reactions and the evolution of cancer." (PMID 40777027, 2025). "It was found that activated TIGIT has a potential activating effect on the activity of apoptosis (47%), epithelial to mesenchymal (EMT) (22%), and hormone estrogen receptor (ER) (31%) pathways in pan-cancer." (PMID 40076932, 2025).
cancer (continued). "Based on the upregulation of other immune checkpoints after PD-1/PD-L1 blockade treatment, we focus on the combination with other ICBs, including CTLA-4, TIM-3, LAG-3, TIGIT, VISTA, and some emerging immune checkpoints, so as to provide evidence for improving the benefit of ICBs in cancers." (PMID 40861801, 2025). "Studies have demonstrated that TIGIT expression levels exhibit a significant negative correlation with the ability of NK cells to secrete IFN-γ in patients with cancer and autoimmune disorders." (PMID 40463500, 2025). "Recently, two novel immune checkpoint molecules, T cell immunoreceptor with Ig and immunoreceptor tyrosine‐based inhibition motif (ITIM)domains (TIGIT), and natural‐killer group 2 member A (NKG2A), have emerged as potential prognostic markers in certain cancers." (PMID 39540362, 2024). "NK cells can become dysfunctional in patients with cancer with reduced expression of NK cell activating receptors such as NKp30, NKp46 and NKG2D and upregulation of inhibitory checkpoint receptors such as TIGIT." (PMID 39286025, 2024). "TIGIT activates a complex immunoregulatory network on binding with its multiple ligands including CD155, CD112, CD113 and Nectin-4 expressed by antigen presenting cells as well as cancer cells." (PMID 38322418, 2024). "While enhancement of HIV-specific CD8+ T cell function by TIGIT blockade did not occur in the majority of cases we tested, the response rate closely matched that seen with in vivo checkpoint inhibition in cancer therapy." (PMID 39770396, 2024). "Furthermore, we assessed the correlations between GBP4 and immune checkpoint genes, including TIGIT, CTLA4, CD274 and PDCD1, across cancers." (PMID 38347243, 2024). "Therefore, further Pearson analysis was conducted to investigate the correlation between GPR65 and common cancer immune checkpoint inhibitors, such as CD200R1, CD47, HAVCR2, TIGIT, CTLA4, LAG3, and PD1." (PMID 38218960, 2024). "It has been found that the anti-programmed cell death protein 1 (PD-1) treatment response in cancer immunotherapy is correlated with CD155 but not TIGIT." (PMID 38229100, 2024). "Interactions of several ligand-receptor pairs between cancer cells and immune cells (CD274:PDCD1, FAM3C:PDCD1, PVR:TIGIT) are predicted to be enhanced in NRF2 signature high samples which could be potential targets to inhibit to remodel the TME." (PMID 38241355, 2024). "However, anti-PD-L1 antibody showed no enhancement of CTL activity in the presence of mesenchymal cancer cells, while the impaired CTL activity was largely restored by anti-CTLA-4 and anti-TIGIT antibodies." (PMID 38914547, 2024). "Given that sCD155 has a higher binding affinity to DNAM-1 compared to TIGIT and CD96, sCD155 might have systemic effects, including regulation of immune responses toward circulating cancer cells or micrometastatic deposits." (PMID 38893071, 2024). "Therefore, we evaluated the expression patterns of TIGIT and CD226 in T and NK cells from cancer patients." (PMID 37596248, 2023). "TIGIT competes with inhibitory receptors KIR2DL5A and PVRIG and activating receptor CD226 (DNAM-1) to bind ligands CD155 (PVR) and CD112 (Nectin-2 or PVRL2) which are commonly expressed on cancer cells and antigen-presenting cells (APCs)." (PMID 37345049, 2023). "The TIGIT/PVR and the TIM-3 pathways have recently been shown to be involved in the macrophage polarization, suppression of pro-inflammatory cytokine production, and cancer cell growth in several mouse models." (PMID 37876933, 2023). "TIGIT, CD226 and CD96 are now broadly explored for possible targets of immunotherapy for cancer." (PMID 37568798, 2023). "Moreover, we have reported that Gal-9-expressing NK cells display impaired cytolytic molecules expression but increased IFN-γ expression dichotomous to TIGIT-expressing NK cells in HIV and cancer patients." (PMID 37006235, 2023).
cancer (continued). "Moreover, we found that KIF18A had a positive correlation with immune checkpoints, such as PD-1, PD-L1, CTLA4, TIGIT, LAG3, HAVCR2, and PDCD1LG2 in a great many cancers." (PMID 36830695, 2023). "While receptor heterogeneity holds true for PVR, the interplay between the receptors i.e. TIGIT blocking CD226 mediated co-stimulation, allows us to envision developing PVR as a dual functioning therapeutic with potential utilization in both cancer and autoimmune therapy." (PMID 36944702, 2023). "teNK cells exhibit increased TIGIT and KLRG1 expression and upregulated DNA methyltransferases, such as DNMT1, DNMT3a, and DNMT3b, compared to healthy NK cells, indicating that epigenetic control by cancer cells occurs in teNK cells." (PMID 37539051, 2023). "Furthermore, positive correlations of PRC1 and some immune checkpoint genes (CD274, CTLA4, HAVCR2, LAG3, PDCD1, PDCD1LG2, TIGIT, and CD86) were observed in several cancers, especially BLCA, BRCA, KIRC, LUAD, LIHC, PRAD and THCA." (PMID 37563591, 2023). "TIGIT can directly inhibit the functions of CD8+ T cell and prevent the clearance of cancer cells." (PMID 37359558, 2023). "Moreover, they have also confirmed that TIGIT conjugated with CD155 on GC cells significantly alters the metabolic reprogramming of CD8+T cells and promotes cancer progression." (PMID 37056782, 2023). "In addition, we also itemized the correlations between TAGLN2 and the major immune checkpoints in pan-cancer, including LAG3, PDCD1, CTLA4, CD274, and TIGIT." (PMID 37476180, 2023). "Combinatorial PD-1 and TIGIT blockade can elicit responses in murine models of PDAC and these findings will help to guide optimal approaches to target TIGIT–CD115/CD112 interactions in cancer therapy." (PMID 36689623, 2023). "Indeed, targeting CTLA-4, TIGIT, PD-1, GITR and other co-inhibitory receptors to limit the function of Tregs possibly is an effective cancer treatment." (PMID 37671150, 2023). "Future experiments should aim to elucidate the connection between TIGIT and other immune checkpoints, particularly those involved in the immune response against cancers which do not express PD-L1, as well as the interplay with HIF-1α and the A2A receptor." (PMID 36874131, 2023). "To determine the functional contribution of M-CSF and CD155 downregulation to carcinogen-induced cancer cell immunogenicity, we examined whether CSF1R and TIGIT blockade could lead to the rejection of DMBA3-4 + DMSO3-1 tumors in WT mice." (PMID 37843274, 2023). "CD226, TIGIT, and CD96 share the same ligand CD155 (also known as PVR/NECL5/TAGE4), a member of the nectin-like family of adhesion molecules and highly expressed on cancer cells." (PMID 37056782, 2023). "Notably, the FCRL family genes demonstrated a significant positive correlation with several immunostimulators, particularly TIGIT, PDCD1, and BTLA, across a range of cancer types." (PMID 37285836, 2023). "In the vast majority of 33 cancers, gene co-expression analysis showed that RIPK2 was positively correlated with the expression of immune checkpoint markers, such as PDCD1 (PD-1), CD274 (PD-L1), CTLA4 and TIGIT." (PMID 35508972, 2022). "The expression of ICs, PD-1 and TIGIT, and of CD39 as well as that of activation and proliferation markers in a population found at higher proportions in cancer patients than in HDs suggested that it could encompass exhausted tumor-Ag-specific T cells." (PMID 35954341, 2022). "Indeed, the roles of TIGIT and CD96 in NK cell depletion in various cancers are still under investigation, and further revelations are required to determine their potential as monotherapy or in combination with other checkpoints." (PMID 35606854, 2022). "The combined application of drugs that block TIGIT and PD-1 (Atezolizumab/Tiragolumab) can upregulate CD8+ T cell expression and function, which may be considered as a potential cancer immunotherapy strategy." (PMID 35585975, 2022).
cancer (continued). "Moreover, correlation analysis hinted at a negative correlation of TMEM59L expression with CD8 T cells, activated CD4 T cells, and several immunomodulators, including IDO1, TIGIT, PD-L1, CTLA-4, and BTLA in various cancers." (PMID 36618425, 2022). "In addition to PD-1/PD-L1 and CTLA-4 as the most important immune checkpoints, emerging evidence indicates LAG3, TIM-3, TIGIT, VISTA, and other immune checkpoints are the representative ones in malignant tumor." (PMID 35991556, 2022). "Moreover, TIGIT expression was found to be positively related to B cell, CD4, CD8 T cell, neutrophil, macrophage and DC infiltration in most cancers based upon the TIMER algorithm." (PMID 36211383, 2022). "Notably, many ongoing clinical trials are attempting to assess the application of TIGIT blockade or TIGIT blockade in combination with anti-PD-1/PD-L1, anti-CTLA-4 or anti-LAG-3 antibodies in the treatments for many cancers." (PMID 35320940, 2022). "No significant prognostic value of TIGIT was found in the OS of cancers, including SCLC, CRC, MTC, ATC, PDTC and PTC." (PMID 36211383, 2022). "We further explored the correlation between the expression of LIPT1 and eight immune checkpoints (PD-L1, CTLA4, HAVCR2, LAG3, PDCD1, PDCD1LG2, SIGLEC15, and TIGIT), and found that LIPT1 levels were correlated with the expressions of these immune checkpoints, especially PD-L1, in most cancer types." (PMID 35837286, 2022). "TIGIT is an inhibitory receptor expressed on CD8+ T cells, Tregs, and NKs and has gained increasing attention as a promising novel pharmacological target for cancer immunotherapy." (PMID 35712510, 2022). "A cancer immunotherapy antibody targeting both CD47 and TIGIT has been patented (WO2020259535)." (PMID 35656508, 2022). "Common immune checkpoint targets that have been reported for having a promising effect, including Lymphocyte activation gene-3 (LAG-3), T cell immunoglobulin and ITIM domain (TIGIT), and indoleamine 2,3-dioxygenase, have presented significance with B4GALNT1 in several cancers." (PMID 35935585, 2022). "Although strategies to neutralize the effect of CD96 are not as advanced as those developed for TIGIT, these studies undeniably demonstrate that the DNAM-1/TIGIT/CD96 axis and CD155 immunoregulation represent promising targetable immunotherapeutic strategies for cancer treatment." (PMID 36231109, 2022). "Furthermore, the expression of TIGIT was correlated with TMB, MSI, MMR genes and DNMTs in different types of cancers." (PMID 34795387, 2021). "TIGIT expression mediated infiltrated immune cells and positively correlated with the expression of LAG3, CTLA4, PDCD1 (PD-1), CD274 (PD-L1), PDCD1LG2 (PD-L2) in most of the cancer types." (PMID 34795387, 2021). "Furthermore, we found that LCK was significantly correlated with TIGIT (total rho=0.82), CTLA4 (total rho=0.77), and PD-1 (total rho=0.81) in most cancer types, indicating the important role of TIGIT, CTLA4, and PD-1 in the TIL-T cells across cancer types." (PMID 35069521, 2021). "PDCD1, CTLA4, TIM3, TIGIT, and LAG3 play key roles in the immune evasion of cancer cells." (PMID 34844217, 2021). "TIGIT competes with the activating receptor DNAM-1 for the ligands CD155 and CD112; thus, blocking TIGIT prevents the exhaustion of cancer-infiltrating NK cells and stimulates potent anti-cancer efficacy." (PMID 34439285, 2021). "Previous studies showed that blockade of TIGIT/PVR signaling could reverse T and NK cell dysfunction in various cancers." (PMID 34150627, 2021). "Further studies with larger cohort should be conducted on patients from different backgrounds and disease states (different MSAs subtypes, with and without cancer) to better elucidate the role of TIGIT+CD226+ CD4 T cell in DM." (PMID 33413573, 2021).